PDPN (podoplanin)
Diseases named in the same sentence as PDPN in open-access papers (continued):
Sharing a sentence is not in itself a finding about the gene and the disease.
breast carcinoma (continued). "However, in breast cancer, it has been reported that PDPN(+) CAFs can diverge into protumorigenic CAFs during tumor progression, or promote resistance to trastuzumab in HER2+ cancer by secreting immunosuppressive factors." (PMID 39764562, 2025). "Additionally, podoplanin-positive CAFs contribute to trastuzumab resistance in HER2-positive breast cancer by secreting immunosuppressive factors, including indoleamine 2,3-dioxygenase 1 (IDO1) as well as tryptophan 2,3-dioxygenase 2 (TDO2)." (PMID 41029829, 2025). "Upregulation of both POSTN and PDPN has been observed in human and canine mammary cancers indicating that for these tumours, in women as in dogs, both proteins as well as Ki67 may have prognostic significance in the course of neoplastic disease." (PMID 41361308, 2025). "PDPN‐positive CAFs could represent a novel therapeutic target for overcoming resistance in HER2‐positive breast cancer." (PMID 38982317, 2024). "Collectively, these studies demonstrate that macrophages expressing LYVE‐1 and associated markers (PDPN, TIM4, STAB1, and FOLR2) may have key roles in the context of breast cancer." (PMID 38426622, 2024). "Moreover, we found that the expression of PDPN and PDGFR-β in CAFs were associated with histological grade of breast cancers and high PDPN (P = 0.0339) or PDGFR-β (P < 0.0001) expression happened in poorly differentiated breast cancer tissues respectively." (PMID 38410801, 2024). "In addition, podoplanin-expressing macrophages (PDPN+ TAMs) are another tumour-specific macrophage subset that has only been reported in breast cancer." (PMID 38303024, 2024). "Furthermore, there was significantly higher PDPN expression in CAFs of HER-2-positive breast cancers (P = 0.0095)." (PMID 38410801, 2024). "Moreover, PDPN-positive CAFs were associated with low IL-2 activity and resistance to trastuzumab in HER2-positive breast cancer patients." (PMID 37894446, 2023). "In addition to OSCC, PDPN promotes a variety of other cancers including mammary carcinoma, glioma, melanoma, ovarian cancer, and pulmonary adenocarcinoma." (PMID 35177067, 2022). "However, in both our models we observe increased numbers of FAPα+ CAFs but significant less PDPN+ CAFs as the tumours developed, underlining the difficulty in dissecting the biological function of FAPα+PDPN+ CAFs in breast cancer." (PMID 34016130, 2021). "For example, neutrophils can promote lung metastasis of breast cancer by secreting leukotriene B4, whereas podoplanin-expressing macrophages can contribute to the lymphoinvasion of breast cancer cells by binding with lymphatic endothelial cells to trigger matrix remodeling and lymphangiogenesis." (PMID 34485309, 2021). "In addition, Tejchman and colleagues proposed that, in a hypoxic environment, podoplanin-positive CAFs facilitate the escape of CCR7-positive breast cancer cells from immunosurveillance by binding of podoplanin to CCL21." (PMID 30736372, 2019). "Podoplanin expression in CAFs is also a marker of poor prognosis for patients with breast cancer." (PMID 30736372, 2019). "Here, we first assessed whether orthotopically growing E0771 murine mammary carcinomas harbor PDPN+ fibroblasts and found that PDPN expression was mainly restricted to cells located at the tumor margin." (PMID 29632733, 2018). "In this study, we have analyzed this process by generating novel transgenic mice that enabled the identification of podoplanin (Pdpn)-expressing lymphatic endothelial cells, as well as the controlled depletion of these cells during lymphangiogenesis in breast cancer progression." (PMID 30592710, 2018). "Therefore, in the present study, the impact of podoplanin expression in fibroblasts on biological properties of breast cancer and endothelial cells was studied." (PMID 28938000, 2017).
breast carcinoma (continued). "Therefore, to avoid the influence of other factors/proteins produced by CAFs and to determine if the biological behavior of breast cancer cells can be affected only by the presence of podoplanin, we used previously established fibroblastic cell lines." (PMID 28938000, 2017). "Moreover, the effect of CCL21 availability to breast cancer cells, through PDPN expression by CAFs, was addressed." (PMID 28416768, 2017). "Therefore, to clarify the functional role of podoplanin present on the surface of CAFs in breast cancer progression, migration and invasion assays involving co-cultures of tumor cells and fibroblasts expressing different amounts of podoplanin were performed." (PMID 28938000, 2017). "Indeed, PDPN expression in CAFs has been correlated with tumor aggression in cancers including mammary carcinoma and lung adenocarcinoma." (PMID 22844530, 2012). "Recently, the D2-40 antibody has been shown to specifically recognize the glomerular podocyte membrane protein Podoplanin, and is a very sensitive and specific marker for lymphatic endothelium in most tissues, especially breast cancer." (PMID 22906075, 2012). "Recently, the D2-40 antibody has been shown to specifically recognise podoplanin, a glomerular podocyte membrane protein and has been shown to be a very sensitive and specific marker for lymphatic endothelium in most tissues and especially in breast cancer." (PMID 17088912, 2006). "For breast cancer, PDPN+-CAFs tended to result in a more malignant pathological status and could facilitate immunosuppression and disease progression, which is consistent with the finding of this meta-analysis study and the findings of PDPN functions in multiple types of solid tumors." (PMID 38410801, 2024). "Podoplanin-null mice have defects in lymphatic vessels formation, which results in diminished lymphatic transport, congenital lymphedema, and the dilation of lymphatic vessels; podoplanin-positive lymphatics were showed to be rate-limiting for breast cancer metastasis." (PMID 35054174, 2021). "Thus, Wicky and coworkers reported that podoplanin stimulates MCF7 breast cancer cell migration in the absence of EMT, an event linked to downregulation of RhoA, RhoC, and Cdc42 GTPase activities." (PMID 30736372, 2019). "Increased numbers of CD11b+Gr1− macrophages in mammary tumors with PDPN+ LEC depletion is also consistent with previous reports on increased macrophage infiltration as a hallmark of lymphedema and could support a potential role of these cells in metastasis, albeit further study is still needed." (PMID 30592710, 2018). "Since it was proposed that podoplanin-expressing CAFs not only affect the motility, but also increase the invasiveness of tumor cells, we analyzed the effect of podoplanin expressed by fibroblastic cells on the invasiveness of breast cancer cells using in vitro MatrigelTM invasion assay." (PMID 28938000, 2017). "LECs were enriched by depleting CD45+ cells from single-cell suspensions and subsequently sorting podoplanin (PDPN)+ CD31+ LECs from distant and metastatic LNs of seven patients with luminal and two with Her2-positive breast cancer." (PMID 41249124, 2025). "Myofibroblastic CAF-S1 and PDPN+ CAF subsets exhibit reduced IL2 activity and contribute to immunosupppression in breast cancer." (PMID 38715072, 2024). "The high expression of α-SMA, PDPN, PDGFR-β in CAFs leads to worse clinical outcomes in breast cancer, indicating their roles as prognostic biomarkers and potential therapeutic targets." (PMID 38410801, 2024). "PDPN positivity correlates with greater invasiveness in lung adenocarcinomas and functionally CAFs expressing PDPN and FAP have previously been identified to suppress T cell proliferation in a nitric oxide dependent manner in breast cancer." (PMID 38582812, 2024). "In human breast cancer patients, co‐expression of SEMA7A, PDPN, and CD68 correlated with metastasis." (PMID 38426622, 2024).
breast carcinoma (continued). "For example, macrophages expressing PDPN, which is also co‐expressed with LYVE‐1 on macrophages, have been found in samples from breast cancer patients and are localized near tumor lymphatics." (PMID 38426622, 2024). "In breast cancer, CAF markers such as FAP, α-SMA, Vimentin, FSP1, PDGFRα, PDGFRβ, Caveolin-1, and PDPN have been validated." (PMID 39519118, 2024). "Using CAF-rich syngeneic lung and spontaneous mammary tumors, NIR-PIT against FAP or podoplanin was performed." (PMID 38275890, 2024). "Analysis of SEMA7A in normal breast tissue from biopsy by IHC.Kaplan–Meier analysis of SEMA7A, PDPN, and CD68 expression in >600 breast cancers, as well as ovarian, lung, and gastric cancer." (PMID 33649008, 2021). "These analyses demonstrate that all six markers identify CAFs in breast cancer, and we therefore designed an antibody panel consisting of the 5 cell surface CAF markers: FAPα, PDGFRα, PDGFRβ, PDPN and CD26." (PMID 34016130, 2021). "Increased PD-L1 expression and PD-L1 T-cells in postpartum patients.Observed co-expression of immune inhibitory PD-L1, PDPN, and CD68 in breast cancer TCGA patients." (PMID 33649008, 2021). "In the present model, breast cancer MDA-MB-231 cells and NKL3 cells express the surface CCR7 receptor for CCL21 chemokine which is a potent chemoattractant able to bind to PDPN." (PMID 28416768, 2017). "We found that CCR7 mRNA expression in human breast cancer tissues positively correlates with the expression of lymphatic endothelial markers LYVE-1, podoplanin, Prox-1, and vascular endothelial growth factor-C (VEGF-C)." (PMID 25744065, 2015). "A comparison of different endothelial lymphatic markers showed that the sensitivity of D2-40 to recognize intratumoral lymphatic vessels on serial sections of breast carcinomas is higher than that of LYVE-1, podoplanin or Prox-1." (PMID 18307818, 2008). "It was found that all lymphatic endothelial markers, LYVE-1, Prox1, podoplanin, 5'-nucleotidase and VEGFR-3, were expressed in significantly higher levels in breast cancers than in normal breast tissue." (PMID 18325094, 2008). "In our study, however, a spike-in assay using recombinant podoplanin (200 ng/ml) demonstrated no significant interference with CLEC-2 quantification in either breast cancer patients or controls." (PMID 41209555, 2025). "In veterinary medicine, PDPN, similar to POSTN, has been recognised and described in some lesions such as mammary carcinoma, keratinising squamous cell carcinoma, melanoma or colon adenocarcinoma, however there is no information about its presence in testicular neoplasms." (PMID 41361308, 2025). "However, the underlying mechanism about the interaction and relationship between PDPN+-CAFs and HER-2-positive breast cancer still needs for further investigation." (PMID 38410801, 2024). "This study, employing a meta-analysis approach, reveals that the high expression of α-SMA, PDPN and PDGFR-β in CAFs may contribute to an unfavorable prognosis of breast cancer patients." (PMID 38410801, 2024). "Furthermore, the high expression of PDPN and PDGFR-β in CAFs is significantly correlated with poor differentiation of breast cancer." (PMID 38410801, 2024). "Additionally, they found that PDPN+CAFs enriched in trastuzumab-resistant tumor tissues and promoted trastuzumab resistance in HER2+ breast cancer by secreting immunosuppressive factors, thereby inhibiting ADCC mediated by functional NK cells." (PMID 39273429, 2024). "Moreover, a significant correlation is found between the high expression of PDPN in CAFs and HER-2-positive breast cancers." (PMID 38410801, 2024). "In human breast cancer, we also found that GPR182 expression was restricted to PDPN+ LECs." (PMID 35013216, 2022). "Moreover, two other CAF subtypes were recently identified in human breast cancer patients using single-cell transcriptomic analysis; FSP-1+ CAFs (sCAFs), and PDPN+ CAFs (pCAFs)." (PMID 34769066, 2021).
breast carcinoma (continued). "Interestingly, in murine and human breast cancers, TEMs express lymphatic markers (e.g., LYVE 1, VEGFR-3, and podoplanin) and lymphangiogenic factors (VEGF-C and VEGF-D) and are associated with lymphatic structures." (PMID 33783686, 2021). "Here, we demonstrate that the depletion of proliferating PDPN-expressing LECs significantly inhibits lymphangiogenesis in mammary tumors, resulting in decreased distant metastasis without an impact on primary tumor growth." (PMID 30592710, 2018). "Human fibroblastic cell lines (MSU1.1 and Hs 578Bst) overexpressing podoplanin and control fibroblasts were co-cultured with breast cancer MDA-MB-231 and MCF7 cells and the impact of podoplanin expressed by fibroblasts on migration and invasiveness of breast cancer cells were studied in vitro." (PMID 28938000, 2017). "It was shown that podoplanin present on the surface of fibroblasts does not directly affect the malignant properties of breast cancer cells, but increases their motility, facilitating in this way the movement of fibroblasts into tumor stroma." (PMID 28938000, 2017). "Migratory and invasive properties of breast cancer cells were not affected by the presence of podoplanin on the surface of fibroblasts." (PMID 28938000, 2017). "Indeed, podoplanin expression can be induced by epidermal growth factor, basic fibroblast growth factor (FGF2) and tumour necrosis factor α in MCF7 breast cancer cells, and by bradykinin in 3T3 fibroblasts." (PMID 17179989, 2007). "However, ectopic expression of PDPN in human fibroblasts did not affect the migratory and invasive properties of co-cultured breast cancer cells." (PMID 39780187, 2025). "Furthermore, PDPN and PDGFR-β expression in CAFs of poorly differentiated breast cancer patients were higher than that of patients with relatively better differentiated breast cancer." (PMID 38410801, 2024). "In conclusion, the high expression of α-SMA, PDPN, PDGFR-β in CAFs led to unfavorable clinical outcomes in breast cancer patients, implicating that all these biomarkers could have potential values in the treatment and prognostic evaluation of breast cancer patients." (PMID 38410801, 2024). "In addition, M-LECPs expressing high levels of LYVE1, PDPN, PROX1 and VEGFR3 were uniquely detected in the lymph vessels of breast cancer tissue and their density correlated with the development of lymphatic metastasis in breast cancer patients." (PMID 33071831, 2020). "Thus, forced podoplanin expression in normal human fibroblasts, although enhancing fibroblast motility, did not affect the migratory and invasive properties of breast cancer cells in co-culture experiments." (PMID 30736372, 2019). "In addition, podoplanin is rarely expressed in breast cancer; thus, platelet activation by podoplanin-expressing tumours might be qualitatively different from that induced by podoplanin-negative tumours." (PMID 28176852, 2017). "For example, although podoplanin can induce RhoA activation and an epithelial-mesenchymal transition (EMT) in MDCK cells, it attenuated RhoA activity and could not induce EMT in a breast carcinoma cell line, suggesting that podoplanin exerts cell type-specific functions." (PMID 21034514, 2010). "Still the other breast carcinoma lines were not able to increase VEGFR-3, CD31 or podoplanin transcripts in HMS-1 cells, yet, in at least some of these other cell lines, VEGF-C transcripts were increased and presumbably VEGF-C was produced." (PMID 21297224, 2010). "For example, markers of myeloid lymphatic endothelial cell progenitors (M-LECPs) were found to be expressed on a portion of lymphatic vessels in breast cancer tissue, but not in normal breast tissue, and M-LECPs co-expressed high levels of PROX1, LYVE-1, podoplanin, and VEGFR-3." (PMID 35054174, 2021). "In addition, CAFs secrete podoplanin (PDPN), which can stimulate angiogenesis and lymphangiogenesis by upregulating VEGF-C but not VEGF-A in breast cancer." (PMID 34294146, 2021).
glioma (64 papers, 2008 to 2026). A benign or malignant brain and spinal cord tumor that arises from glial cells (astrocytes, oligodendrocytes, ependymal cells). "PDPN is a transmembrane receptor glycoprotein which is used as a diagnostic marker in several types of cancer, including glioma, squamous cell carcinoma, mesothelioma, and melanoma." (PMID 40394416, 2025). "High levels of PDPN expression increased the risk of high-grade gliomas and reduced patient survival time, predicting a worse prognosis (HR = 5.354, 95% CI 3.57–8.031)." (PMID 40554484, 2025). "In patients with IDH1-mutated gliomas, the expression levels of tissue factor (TF) and podoplanin (PDPN) are lower, and high expression of these proteins is associated with increased VTE risk." (PMID 40873733, 2025). "Adjusted for multifactorial cox regression, PDPN (HR = 2.348, 95% CI 1.003–5.497) remained a risk factor for poor prognosis in high-grade gliomas; while Grade (HR = 7.353, 95% CI 4.6–11.752) also acted as a risk factor." (PMID 40554484, 2025). "Another study investigated the expression of PDPN in glioma tissues and its association with prognostic factors." (PMID 39682237, 2024). "Linear regression analysis revealed that the number of CD68‐positive cells was significantly positively correlated with the number of GFAP+PDPN+ cells in glioma, with CD68+CD163+ cells showing a similar association with GFAP+PDPN+ cells." (PMID 38470096, 2024). "IDH1 mutation in brain lower grade glioma associates with lower lymphangiogenesis and metastasis possibly by down regulating PDPN gene expression." (PMID 38241355, 2024). "High expression of PDPN has been associated with a poorer prognosis in gliomas, PDPN is most abundant in glioblastomas and therefore is considered as an important target for CAR-T cell therapy of brain tumours." (PMID 39046631, 2024). "Their findings suggested that PDPN serves as an independent prognostic marker in glioma patients, and its expression is associated with resistance to radiotherapy and the aggressiveness of tumors." (PMID 39682237, 2024). "Bulk RNA‐seq data analysis indicated that PDPN was associated with macrophage M2‐like polarization in gliomas." (PMID 38470096, 2024). "Multiple linear regression analysis was performed on the mutation status of the genes with the top 20 mutation frequencies in glioma and the expression level of PDPN." (PMID 36434176, 2023). "Intriguingly, PDPN has been implicated in malignant progression and invasion of a variety of human cancers, including gliomas." (PMID 36434176, 2023). "PDPN expression is highly elevated in several cancers, including squamous cell carcinoma of the head and neck, gliomas, and colon cancer and is associated with poor survival outcomes." (PMID 34879110, 2021). "Downregulation of PDPN has been observed in glioma carrying IDH1 mutations, which can increase chances for survival in patients carrying IDH1Mut38." (PMID 33221817, 2020). "For example, about 14% of patients with primary brain tumors (mostly high-grade gliomas) develop venous thromboembolism, an event strongly associated with overexpression of podoplanin." (PMID 30736372, 2019). "Previously, the glioma-associated myeloid compartment has been reported to express the transmembrane protein podoplanin (PDPN)." (PMID 30972297, 2019). "For example, a higher glioma grade as well as distinct local tumor characteristics, such as the upregulation of podoplanin expression on tumor cells, are associated with a higher VTE risk." (PMID 31847343, 2019). "Taken together, we describe a population of immune-inhibitory tumor-associated PDPN+ myeloid cells, which contributes to the poor prognosis in high-grade glioma." (PMID 30972297, 2019). "In this study we investigated the function of a tumor-associated myeloid cell subpopulation characterized by podoplanin expression on the development of high-grade glioma tumors." (PMID 30972297, 2019).